ARG1 (arginase 1)
Diseases named in the same sentence as ARG1 in open-access papers (continued):
Sharing a sentence is not in itself a finding about the gene and the disease.
tumor (continued). "In tumor masses, microglia have native activity and can stimulate tumor growth by several cytokines and chemokines, such as IL-10, monocyte chemoattractant protein-1 (MCP-1/CCL2), some metalloproteinases (MMPs), and ARG1." (PMID 37170286, 2023). "As HD exosomes carried similar levels of Arg-1 compared to HNSCC exosomes, tumor cells cannot be the only cells releasing Arg-1 via exosomes." (PMID 38001706, 2023). "On the other hand, TANs also exhibit anti-tumor properties, including direct killing of nascent tumor cells, releasing Arg1 to stimulate TRAIL expression and induce tumor cell apoptosis, and recruiting and activating T cells for tumor cell eradication." (PMID 38204755, 2023). "According to RT-qPCR analysis, the expression of the pro-tumor macrophage markers CD206, CD163, IL-6, IL-10, Arginase-1, and TGF-β were downregulated compared to the normal control group." (PMID 38098044, 2023). "A previous study has shown that, interleukin-6 (IL-6), a tumour-promoting cytokine in the TME, can induce microglia M2-like polarisation by increasing ARG1 expression." (PMID 37462801, 2023). "The expression of DNA‐PK and functional markers of MDSCs (iNOS, Arg1, and IDO) in splenic MDSCs from tumor‐bearing mice treated with NU7441 in vivo was significantly increased, which was consistent with the results of NU7441 administration in vitro." (PMID 36373232, 2023). "It has been reported that lactate generated from tumor cells can activate the production of vascular endothelial growth factor (VEGF) and arginase 1 (Arg1), promoting TAM polarization to M2 and assisting TAM in promoting tumor growth." (PMID 37646027, 2023). "Neutrophils can also reduce the arginine in T cells by secreting arginase-1(ARG-1), thereby inhibiting the activation and proliferation of CD3 mediated T cells, ultimately leading to tumor proliferation." (PMID 37152022, 2023). "Tsai and colleagues reported that after irradiation, Arg‐1, COX‐2, and inducible nitric oxide synthase (iNOS) are overexpressed in TAMs, which stimulates tumor growth." (PMID 37347290, 2023). "For example, LIC has been reported to exert anti-tumor effects by targeting PI3Kγ-AKT signaling pathway, reducing the expression of Arg1 and ROS, promoting apoptosis of MDSCs cells, and reducing the inhibition of CD8 + T cells." (PMID 37217620, 2023). "The expression of Arg1 and TGF-β in peripheral blood G-MDSCs began to significantly increase after 3 weeks of tumor bearing." (PMID 35013108, 2022). "On the other hand, iNOS production, apart from showing anti-tumour activity, can acts by suppressing anti-tumour immunity as well, suppressing effector CD8+ T cell along with arginase 1 (ARG1) and resulting in tumour progression." (PMID 35406451, 2022). "MiR-21 in exosomes or extracellular vesicles induced by GBM tumor cells can be incepted by GAMs and upregulate IL-6, TGF-β, and Arg-1 in M2 GAMs, resulting in downregulating the immune response and accelerating growth and invasion of GBM tumor cells." (PMID 35572545, 2022). "Reduced levels of arginase 1, TGF-β and IL-10 in the tumor also provided evidence for reversion of the immunosuppressive conditions by VSV-S infection." (PMID 35197076, 2022). "Tumor progression was accompanied by the increased percentage of YFP+CD45+CD11b+ myeloid cells, i.e. producing ARG1, both in the bone marrow and the spleens." (PMID 36385153, 2022). "M2 macrophages express numerous anti-inflammatory molecules, including ARG-1, TGF-β, and IL-10, promoting tumor immunosuppression and progression." (PMID 35889289, 2022). "Of note, significantly lower expression of Arg1 and higher expression of CD86 were found in healthy cortex compared with tumor tissue." (PMID 35884700, 2022). "The arginase 1 inhibitor INCB001158 promotes T-cell infiltration and inflammatory cytokines production in the TME in the mouse tumor models." (PMID 36231064, 2022).
tumor (continued). "We found that MyD88 inhibitor administration reduced iNOS, Arg-1 and IDO expression to weaken tumor-immune evasion mediated by MDSCs." (PMID 35089465, 2022). "Studies have shown that lactate derived from tumor cells can induce the expression of vascular endothelial growth factor (VEGF) and arginase 1 (ARG1) through the HIF1A signaling pathway and promote the polarization of TAM to M2-like." (PMID 35281061, 2022). "In several mouse tumor models, the phosphodiesterase-5 (PDE5) inhibitor sildenafil, tadalafil and vardenafil downregulates the expression of ARG1 and iNOS, reversing MDSC-induced immunosuppression and restoring antitumor immunity." (PMID 36163047, 2022). "The microRNA let-7a, found in tumor exosomes, inhibits mTOR signaling in TAMs, leading to increased OXPHOS and expression of the M2-like markers CD206 and arginase-1." (PMID 34876704, 2022). "Arginase-1 (Arg-1), a recent marker for HCC, is involved in the urea cycle leading to polyamines production and tumor cell proliferation." (PMID 35081125, 2022). "By overexpressing vascular endothelial growth factor, CD204, CD163, MMPs, and arginase-1 immunomodulatory molecules and releasing immunosuppressive molecules, they promote STAT3 expression and tumor cell growth, and inhibit their antigen presentation function." (PMID 36411434, 2022). "The mRNA expression of the M1 (iNOS and CD86) and M2 markers (ARG1 and CD206) in tumor tissue was analyzed by RT‐qPCR." (PMID 34861103, 2022). "Both NSCLC tumor lysates and ANXA2 protein induced ARG1 mRNA expression by approximately 2-fold in naive HDNs." (PMID 36377658, 2022). "Astragalus polysaccharide can reduce the number of MDSCs and the expression of MDSC-related Arg-1 and TGF-β, thereby controlling tumor growth in melanoma-bearing mice." (PMID 36686745, 2022). "Studies have shown that knockdown of lncRNA Pvt1 reduced the levels of Arg1 and ROS in G-MDSC and partially restored the anti-tumor T cell response." (PMID 35222443, 2022). "The intracellular level of ARG1 was significantly higher in SP-PMNs in both PL- and LLC-tumor-bearing mice." (PMID 36377658, 2022). "The expression of other M2 marker genes, including Arg‐1, IL‐10, CCL8, Fizz1 and YM‐1, were also upregulated in the tumor from Senp3 cKO mice, as demonstrated by qRT‐PCR analysis." (PMID 33932085, 2022). "IDO, ARG-1, iNOS and COX2 are enzymes expressed by tumor-infiltrating myeloid cells, which have been under investigation since they are considered to be strongly connected to immunosuppressive functions." (PMID 35328639, 2022). "Stimulated by TGF-β, TANs can produce NO or arginase-1, which inhibit the immune response and the infiltration of CD8+ T lymphocytes into the tumor environment." (PMID 36230676, 2022). "TMAs facilitate the ICs expression on tumor cells or produce IL-10, TGF-β, Arg-1, and IDO to impede T cell function." (PMID 36246629, 2022). "In a mouse model of PDA, Clec7a deletion significantly reduced the infiltration of PDA with F4/80+, CD206+ and Arg1+ TAMs, as well as upregulated MHCII, TNF-α and iNOS expression in tumor." (PMID 36686729, 2022). "To determine the mechanism by which ARG1 mRNA is induced in TANs, we utilized FPLC followed by MS/MS to screen tumor-derived factors capable of inducing ARG1 mRNA expression in neutrophils." (PMID 36377658, 2022). "The expression of TGF‐β, p‐SMAD2, and three tumor proliferation markers (p‐PI3K, p‐p38, and p‐ERK1/2) exhibited a similar trend as that of Arg1." (PMID 35128843, 2022). "Our results demonstrate that arginine deprivation specifically altered the expression of Arg1 and iNOS in the GAMM population, thereby altering their polarity toward a phenotype more capable of targeting the GBM tumor." (PMID 35113813, 2022). "Aberrant expression of Arg1 in the TME and in tumour macrophages has been found to correlate with tumour growth, metastasis, and poor prognosis in many types of cancers." (PMID 36497272, 2022).
tumor (continued). "The end-product of tumor cell glycolysis is lactate, which promotes the production of VEGF and arginase-1 in TAMs to support tumor vascularization and proliferation." (PMID 34876704, 2022). "It was shown that tumor cells can act through vesicular ARG1 beyond the TME, transferring functionally active ARG1 over long distances to the local lymph nodes, the key site of T cell activation and proliferation upon antigen recognition." (PMID 35563789, 2022). "ARG-1 and NOS2 use L-arginine as a substrate and deplete L-arginine from the tumor microenvironment, producing nitric oxide and ROS, mediating T cell suppression." (PMID 35873573, 2022). "Concomitant events include the secretion of tumor-promoting pro-inflammatory cytokines (IL-6, TNFα and IL23) and the production of immune suppressive factors (e.g., Arg1, TGFβ, and IDO)." (PMID 35237269, 2022). "CAM-type macrophages express MHC II, CD86, NO, iNOS, showing the characteristics of pro-inflammatory response and anti-tumor, while AAM-type macrophages express IL-10, arg-1, CD206, CD163, TGF-β, showing immunosuppressive and tumor-promoting characteristics." (PMID 36439090, 2022). "A study in syngeneic MM model indicated that ARG1 might play a role in suppressing antitumor immune response—intraperitoneal (i.p.)administration of recombinant ARG1 into mice with NS-1 MM significantly shortened the survival of tumor-bearing animals and impaired NK cells activity." (PMID 36385153, 2022). "Curcumin remarkably inhibits the expression of arginase-1 (Arg-1) and ROS of MDSC in tumor tissues, and also decreases IL-6 in serum and tumor tissues of LLC-bearing mice to prevent the multiplication of MDSC." (PMID 36439106, 2022). "ARG-1 inhibitor (CB-1158) decreased MDSC recruitment in TME, increased tumor-infiltrating T cells and NK cells, reduced tumor burden in preclinical models." (PMID 35122833, 2022). "In hypoxic zones, breast cancer cells produce Oncostatin M (OSM) that induces macrophage polarization toward a tumor-promoting phenotype (higher expression of CD163, CD206, Arg1 and Cox-2)." (PMID 35309358, 2022). "Previous studies have shown that expression of ARG1 was closely related to HCC differentiation, histological type, Edmondson grade, and other indicators that indicate the degree of tumor differentiation." (PMID 36212404, 2022). "The single exception was arginase 1 (Arg-1), a marker of myeloid-derived suppressor cells (MDSCs), which was expressed more highly in the HMGB1-knockout tumor tissues than the WT tumor tissues." (PMID 35150340, 2022). "We thus detected the ROS and H2O2 concentration and the expression levels of ARG-1 mRNA, iNOS mRNA of Ly6G+Ly6C+ MDSC which were sorted from tumor-bearing mice, as described in the Materials and Methods section." (PMID 36159871, 2022). "Treatment with FA-TLR7-1A nearly doubled the ratio of M1:M2 macrophages (as measured by the iNOS:arginase 1 ratio) and halved the percentage of MDSCs in the live CD45+ tumor cell population." (PMID 35250995, 2022). "In contrast, LL-37, ARG1, PGLYRP1 and S100A12 also exhibit antitumor activity affecting tumor cells directly or through the modulation of specific immune and nonimmune stromal cell populations." (PMID 36230605, 2022). "Depletion of L-arginine by induced ARG1 in TAMs leads to the downregulation of CD3ε expression on the T-cells surface which results in TCR inactivation and failure to recognize tumor antigens." (PMID 36679900, 2022). "TAMs can recognize dying tumor cells through the MER tyrosine-protein kinase (MERTK) receptor and upregulate the expression of wound-healing factors such as TGF-β, IL-10, and ARG1 that suppress anti-tumor immunity." (PMID 34603327, 2021).
tumor (continued). "Loss of SMAD4 promotes expression of CCL15 by CRC and recruitment of CCR1+ TANs (CCL15-CCR1 axis) with both arginase-1 (ARG-1) and matrix metalloprotease 9 (MMP-9) activity, forming a premetastatic niche for the disseminated tumor cells —e.g., in the lungs." (PMID 33917620, 2021). "Arginase-1 (Arg-1) is an immunosuppressive factor expressed by MDSCs that suppresses CD8+ T cell function and anti-tumor immune responses." (PMID 33717093, 2021). "In the Cox model including additionally ARG1 mRNA level and tumor stage, the effect of HPV positivity to OS was not significant most likely due to the correlation of higher tumor stage and HPV negativity." (PMID 33807310, 2021). "Both Resveratrol (RSV) and Dendrosomal Curcumin (DNC) are revealed to downregulate the expression levels of IL-10 and Arg1 on TAM through the inactivation of STAT3 to reduce the numbers of TAM, further inhibiting tumor growth and metastasis." (PMID 33748122, 2021). "Within the tumor microenvironment induced by C. parvum, upregulated expression of immune suppressive factors such as ARG1 and SPP1 probably indicates the presence of tumor promoting M2 TAMs." (PMID 34946170, 2021). "The tumor compartment of primary samples had significantly higher expression of immune cell markers CD45, CD8, ARG1, GZMB, BIM, BCL2, showing brain metastases have very few immune cells infiltrating in the tumor epithelium." (PMID 34838031, 2021). "Celecoxib in combination with IFNγ reduced the expression of MMP-2, MMP-9, and VEGF-A in tumor and decreased MVD, mediated by the increased amount of CD68+iNOS+ M1 macrophages and by decreased amount of CD68+Arg1+ M2 macrophages in mouse model of LLC." (PMID 34209679, 2021). "Promotes the activation of C/EBPβ and upregulates the expression of arginase-1, NO synthase 2, NADPH oxidase 2, and cyclooxygenase-2, which are related to the immunosuppressive function of MDSCs in inflammatory and tumor environments." (PMID 34295338, 2021). "Reagents blocking ARG1 activity, such as CB-1158 and ADI-PEG 20, can dampen the TIM-induced immune evasion and inhibit tumor progression." (PMID 34988072, 2021). "We show marked reductions in Pdcd1l1, Arg1, Il10 and Tfgb1 in PMN-MDSCs from bone marrow and spleen of tumor-bearing mice." (PMID 34531850, 2021). "Arginase 1 expression in malignant cells and myeloid cells in the TME represents a powerful mechanism for tumor immune evasion." (PMID 34504786, 2021). "Tumor-derived lactate, a byproduct of tumor glycolysis, leads to M2-like TAM polarization by activating HIF-1α and subsequent inducing ARG1 and VEGFA." (PMID 34389031, 2021). "Studies in neuroblastoma mouse models have reported the accumulation of MDSC during tumor progression and that MDSC-released factors including Reactive oxygen species (ROS)-, Arg-1-, and TGF-β-mediated tumor growth." (PMID 33917501, 2021). "Triptolide selectively inhibited macrophage differentiation toward the M2 phenotype through downregulation of CD206, arginase 1, and CD204, secretion of anti-inflammatory cytokines, and abolished M2 macrophage-mediated tumor progression." (PMID 34948368, 2021). "Tumor-infiltrating monocytic-lineage cells from ATRX KOs expressed less class II HLA and higher levels of Arg1, Vegfa, and other markers of the immunosuppressive M2 phenotype." (PMID 34763709, 2021). "The treatment of tumor bearing mice (CT26, 4T1, B16, and LLC) with CB-1158, a small molecule inhibitor of ARG1, elicited increased cytotoxic T cell infiltration and decreased myeloid cell numbers." (PMID 33747948, 2021). "Arg1 and Odc1 was reduced in cured mice (p < 0.05 for low dose BCG cured versus tumor bearing mice)." (PMID 34944584, 2021). "We then examined the changes in M2-like TAM markers (CD163, CD206, CD209, IL-10 and Arginase 1) and M1-like TAM markers (CD80, CD86, IL-12, and TNFα) induced by CM from ILT4-downregulated tumor cells." (PMID 33537094, 2021).
tumor (continued). "We detected more arginase 1 producing M2 TAMs (M2-ARG) in the stroma of HPV− patients (p = 0.003) while the level of M2-ARG in the tumor parenchyma was comparable in both groups (p = 0.0843)." (PMID 33807310, 2021). "In cancer, however, both ARG1 and IDO1 are overexpressed, in MDSCs and DCs, and contribute to the impairment of the host anti-tumor immunity." (PMID 34389039, 2021). "In vivo study showed that tumor-associated neutrophils (TANs) were significantly infiltrate into tumor tissues of mouse model, with up-regulated CXCLs/CXCR2 signaling and suppressive molecules, including Arg-1 and TGF-β." (PMID 33814009, 2021). "In neoplastic diseases, MDSCs are major contributors to the intra-tumoral arginase activity observed in both preclinical models and cancer patients, in which tumor-derived factors, such as PGE2, can induce Arg1 expression via STAT3 or STAT6." (PMID 34037806, 2021). "By enhancing the expression of arginase-1 and IDO, which delete the arginine and tryptophan in the TME, TADCs attenuate the tumor-fighting function of effector T lymphocytes, supporting the immune evasion of leukemia cells." (PMID 34868994, 2021). "The expression of M1 macrophage markers iNOS, IL-1β, TNF-α and CD86 was increased, and the expression of M2 macrophage markers IL-10, Arg-1 and CD206 was reduced in the tumour tissues of tumour-bearing mice." (PMID 34726570, 2021). "High expression of ARG1 and ARG2 was detected in malignant cells and tumor-infiltrating microglia/macrophages (MG/MΦ)." (PMID 34504786, 2021). "Tumor associated neutrophils, a subset of the myeloid-derived suppressor cells (MDSCs), promote an immunosuppressive environment by secreting arginase-1 (Arg1) or indoleamine 2,3-dioxygenase (IDO), therefore limiting T cell mediated killing of tumor cells." (PMID 34771611, 2021). "In tumor tissue, mainly pro-tumorigenic, M2-like M-MDSCs are the dominant type, which inhibit tumor cell killing mediated by cytotoxic T lymphocytes primarily through IL-10, TGF-β, and ARG1." (PMID 33918295, 2021). "Since arginase-1 (ARG-1) and nitric oxide synthase 2 (NOS2) activation leads to the suppressive effects of MDSCs, we next checked the expression of ARG1 and NOS2 in the tumor collected from the treatment groups." (PMID 34381456, 2021). "We observed that ILT4 knockdown in tumor cells decreased M2-like markers, including CD163, CD206, IL-10, and Arginase 1 but increased M1-like markers including CD80, CD86, IL-12, and TNFαin TAMs." (PMID 33537094, 2021). "Pro-tumorigenic TAMs produce an array of inhibitory molecules such as ARG1, IL-10, and IDO that exert immunosuppression functions, and angiogenesis factors, such as VEGF and TGF-β that promote tumor progression." (PMID 34988072, 2021). "We used RT-PCR and western blotting to determine the relative expression levels of ARG1 and NOS2 in HLA-DR-mononuclear cells in the peripheral blood and tumor tissues of GC patients." (PMID 32415175, 2020). "This is also reflected by strong positive correlation (Pearson 0.92) between ARG1+ and CD11b+CD15+ myeloid cell densities in tumor ROI." (PMID 33193316, 2020). "Remarkably, mice receiving AdIL-17A-transduced 4T1 tumors had a massive accumulation of Arg1+ and PD-L1+ granulocytic and monocytic MDSC populations by day 14 post tumor inoculation." (PMID 32770025, 2020). "Supernatants from tumor cells experiencing endoplasmic reticulum (ER) stress and unfolded protein response (UPR) was shown to induce ARG1 in DCs." (PMID 32499785, 2020). "PGE2 is involved in inflammation, angiogenesis, tumour progression via recruitment of MDSC, and is also involved in the expression of one of the primary immunosuppressive mechanisms employed by MDSC: ARG1." (PMID 32121014, 2020). "Compared to normal mucosa, ARG1, PRMT1, and PRMT5 were overexpressed in both tumor and tumor-adjacent tissue and DDAH2 solely in tumor-adjacent tissue." (PMID 32932854, 2020).